PCSK9 (proprotein convertase subtilisin/kexin type 9)
Diseases named in the same sentence as PCSK9 in open-access papers (continued):
Sharing a sentence is not in itself a finding about the gene and the disease.
cancer (continued). "Analysis of mRNA expression in TCGA paired samples revealed notably enhanced levels of LDHA, SHC1 and CDKN3 in cancer tissues compared to adjacent tissues, whereas PCSK9, BTK, CAV2 and PDGFB showed significantly reduced expression." (PMID 40182622, 2025). "PCSK9 plays a crucial oncogenic role in various cancer-related processes, including cell proliferation and survival, invasion, metastasis, resistance to radiation therapy, and tumor immune response." (PMID 40362754, 2025). "Contrary to some prior studies, we found little evidence to support associations of other lipid-perturbing targets (eg, PCSK9, CETP) with cancer risk (eg, breast, prostate, head and neck)." (PMID 40511612, 2025). "We then injected two million 231‐GFP or 4–11 cells into the mammary fat pads of NOD/SCID mice and let these cancer cells grow into primary tumors in 6 weeks, Afterward, we used ELISA assay to measure the protein levels of PCSK9 in the serum of the mice." (PMID 40192514, 2025). "Correspondingly, PCSK9 inhibition was illustrated to strengthen the treatment effects of cancer immunotherapy." (PMID 40872487, 2025). "Accordingly, clinical studies investigating the therapeutic potential of PCSK9 inhibitors to enhance treatment efficacy are actively underway across various carcinomas." (PMID 41228357, 2025). "Despite its integral role in cholesterol regulation, PCSK9 has been increasingly highlighted in cancer research over the last decade, especially following our discovery that PCSK9-iTs can augment immune checkpoint therapy for cancer treatment." (PMID 38185721, 2024). "In summary, the fusion of PCSK9 inhibition and anti-PD-1/PD-L1 immunotherapy heralds a new era in cancer therapeutics, with the promise of a safer, more patient-friendly, and potentially more effective treatment option." (PMID 39324018, 2024). "Based on these findings, drugs inhibiting PCSK9 seem to potentially serve as crucial cardioprotective strategies for mitigating ASCVD in cancer patients undergoing ICI therapy." (PMID 38473748, 2024). "Combining PCSK9 inhibition with anti-PD-1/PD-L1 immunotherapy represents a promising approach for cancer treatment." (PMID 39324018, 2024). "And PCSK9 antibodies synergize with anti-PD1 therapy in suppressing tumor growth in mouse models of cancer." (PMID 38850359, 2024). "Emerging data have revealed that PCSK9 plays a key role in lipid-centric cardiovascular diseases and has novel roles in cancer cell proliferation, apoptosis, invasion, and metastasis." (PMID 39282119, 2024). "According to the latest studies, inhibiting PCSK9 is a promising way to enhance immune checkpoint therapy for cancer." (PMID 39282119, 2024). "This review concentrates on the relationship between PCSK9 and cholesterol metabolism, systematically discusses how PCSK9 inhibition potentiates PD-1/PD-L1 blockade for cancer treatment, and highlights the research directions in this field." (PMID 39324018, 2024). "This section reviews the current clinical trials evaluating the efficacy and safety of PCSK9 inhibition and anti-PD-1/PD-L1 immunotherapy in different types of cancer and discusses the potential benefits and challenges of this novel therapeutic approach." (PMID 39324018, 2024). "The potential influence of PCSK9-iTs on human cancer or TIME, either as standalone treatments or in combination with other therapies, is another research area to probe into." (PMID 38185721, 2024). "Liver diseases, including cancer, are treated using dSaCas9-KRAB and dCas9-cre-CRISPRa systems, which target genes like Pcsk9 and proto-oncogenes, offering advances in cholesterol management and cancer genetics." (PMID 39726634, 2024). "In recent years, extrahepatic studies on PCSK9 have become a new direction of interest involving cardiomyocyte, macrophage, endothelial cell, and cancer cell metabolism, thus revealing the existence of a wider range of applications for PCSK9 targets." (PMID 38887452, 2024).
cancer (continued). "Our aim was to enhance the understanding of the role of PCSK9 inhibitors in oncogenesis and to provide theoretical insights for their clinical application in cancer therapeutics." (PMID 38275613, 2024). "The discovery of HLA-A2 as a new target of PCSK9 led to the combination of PCSK9 inhibitors or antibodies with PD-1 antibodies in cancer therapy." (PMID 38786080, 2024). "These approaches can provide new evidence for the application of PCSK9 inhibitors in treating malignant tumors." (PMID 38275613, 2024). "This emerging data makes PCSK9 inhibitors a plausible consideration for future trials to evaluate their clinical effect as an adjunct therapies for various cancers, especially those in which immune therapy have proven efficacious." (PMID 38672532, 2024). "In summary, PCSK9 expression was aberrantly higher in tumor tissues and related to later disease stages in most types of cancer." (PMID 38600469, 2024). "PCSK9 has emerged as an attractive target for cancer therapy, as its expression in both tumor cells and CD8+ T cells can suppress tumor progression by modulating cholesterol metabolism." (PMID 39402302, 2024). "Leveraging innovative technology, PCSK9 depletion in four mouse cancer cell lines significantly reduced their tumorigenic abilities compared to PCSK9VC cells in syngeneic mice." (PMID 38185721, 2024). "PCSK9 has abnormal expression in a variety of cancer types and plays a critical role in both carcinogenesis and cancer immunity." (PMID 38540127, 2024). "Although miR-337-3p, miR-483 and miR-552-3p have been identified to reduce serum LDL-C level in mice by targeting PCSK9, miR-483 and miR-552-3p have been found to stimulate cell proliferation, migration and invasion of cancer." (PMID 39628814, 2024). "For instance, in conditions such as neuroglioma and NSCLC, the silencing of the PCSK9 gene has been shown to activate cancer cell apoptosis through pathways involving caspase-3 and XIAP/p-Akt." (PMID 38473748, 2024). "It suggests that inhibiting PCSK9 not only affects cholesterol metabolism but also modulates the immune response, making it a multifaceted target for cancer treatment." (PMID 39324018, 2024). "For instance, further research is needed to explore PCSK9’s actions on cancer cells, its molecular signaling within TIME, and its roles in the modulation of antitumor immunity." (PMID 38185721, 2024). "Further preclinical and clinical studies are needed for PCSK9 vaccines to ensure the efficacy and safety of therapeutic inhibition of PCSK9 in patients with different types of cancers." (PMID 39736777, 2024). "Several studies have suggested a role of proprotein convertase subtilisin/ kexin type 9 (PCSK9) in cancer biology and metastasis." (PMID 38167685, 2024). "In conclusion, the convergence of PCSK9 inhibition with anti-PD-1/PD-L1 immunotherapy presents a multifaceted approach to cancer treatment, offering a tapestry of benefits that extend beyond the conventional therapeutic modalities." (PMID 39324018, 2024). "The disruption of MHC I recycling by PCSK9 has important implications for cancer immunotherapy, as it reduces the capacity of tumor cells to present antigens to CD8+ T cells and evade immune surveillance." (PMID 39324018, 2024). "Whilst most studies focus on its role in atherosclerosis, there is a growing interest in the involvement of PCSK9 in cancer, particularly regarding its contribution to increased cholesterol levels and as a suppressor of the immune response." (PMID 38611089, 2024). "It was found that, out of the 17 available cancer datasets, PCSK9 mRNA significantly overexpressed in nine cancer types." (PMID 38185721, 2024). "The cholesterol-lowering effect of PCSK9 inhibitors is considered a potential mechanism against cancer." (PMID 38822303, 2024). "The interference of TCR recycling and signaling by PCSK9 has important implications for cancer immunotherapy, as it reduces the capacity of T cells to respond to tumor antigens and exert cytotoxic effects." (PMID 39324018, 2024).
cancer (continued). "Apart from cholesterol metabolism regulation, PCSK9 promotes evasion of immune system and inhibition of inflammation in cancer, which is in concordance with the increased plasmatic membrane expression of PCSK9 here observed by IF." (PMID 36745330, 2023). "To evaluate the association between PCSK9 expression and immune infiltration, we further investigated the relationships between the PCSK9 expression and immune cells in three different cancers (BLCA, BRCA, and LIHC) from the TIMMER database." (PMID 37860186, 2023). "PCSK9 is known as a regulator of the metabolism of LDL-c, although thus far its role in cancer susceptibility has yet to be comprehensively evaluated and characterised." (PMID 36595504, 2023). "With PCSK9 emerging as an important oncogenic factor, it presents an appealing opportunity to target PCSK9 for cancer therapy." (PMID 36588164, 2023). "The correlation between the expression levels of PCSK9 protein and immune cells in pan-cancer tissues were analyzed using the TIMER database." (PMID 37860186, 2023). "This novel finding highlighted that PCSK9 inhibition was a potential strategy for improving immune checkpoint treatment for cancer." (PMID 37860186, 2023). "We used the following terms: "PCSK9", "Cancer", "Immune Checkpoint", and "Cancer Prognosis" in the title and/or abstract." (PMID 38864086, 2023). "Recently, a pivotal role for PCSK9 in cancer immunotherapy was proposed based on the finding that PCSK9 inhibition was associated with enhancing the antigen presentation efficacy of target programmed cell death-1 (PD-1)." (PMID 37860186, 2023). "The PCSK9 gene is located on chromosome 1p32.3 that is expressed in several organs, including the liver, kidneys, small intestine, heart, and cancer cells." (PMID 36900189, 2023). "Further investigations and clinical trials are warranted to validate the utility of PCSK9 as a reliable biomarker and explore its potential role in guiding immunotherapeutic interventions for cancer treatment." (PMID 37860186, 2023). "PCSK9 expression is elevated in a variety of cancers, and knockout of PCSK9 inhibits tumor cell proliferation, induces apoptosis, inhibits tumor growth in mice, and prolongs survival in tumor-bearing mice." (PMID 37762693, 2023). "Recent preclinical and clinical evidence supports the anticancer and immune-stimulating properties of PCSK9 inhibition therapy through the inhibition of peritumoral peripheral immune tolerance and reduction of cytokines involved in cancer cell survival." (PMID 36900189, 2023). "Specifically, PCSK9 was extensively genetically altered across most cancer types and was consistently found in different tumor types and substages when compared with adjacent normal tissues." (PMID 37860186, 2023). "The interaction between PCSK9 and EVs in tumorigenesis was interesting, but due to limited research, our pan-cancer analysis cannot reveal this point." (PMID 37860186, 2023). "This knowledge is likely important in targeting PCSK9 in cancer therapy (see Discussion for details)." (PMID 36588164, 2023). "While arguing for targeting PCSK9 in cancer immunotherapy, these considerations also raise the concern that statins have the potential to interfere with immune checkpoint blockade via activation of SREBP and upregulation of PCSK9." (PMID 37568764, 2023). "Proprotein convertase subtilisin/kexin-9 (PCSK9) has been primarily studied in the cardiovascular field however, its role in cancer pathophysiology remains incompletely defined." (PMID 37860186, 2023). "Since PCSK9 has a potential role as an important new target for cancer diagnosis and prognosis, we analyzed the PCSK9 mRNA levels across different cancers from TIMER, GEPIA, and UALCAN databases." (PMID 37860186, 2023). "Another significant discovery was the correlation between PCSK9 expression and various infiltrating types of immune cells in the majority of cancer types." (PMID 37860186, 2023).
cancer (continued). "Our research thus calls for caution in targeting PCSK9 in the circulation with anti-PCSK9 antibodies and PCSK9 vaccine in cancer patients." (PMID 36588164, 2023). "Recently, it was demonstrated that PCSK9 regulates proliferation and apoptosis in human cancer cells." (PMID 36900189, 2023). "For example, in neuroglioma and NSCLC, knockdown of PCSK9 gene activates cancer apoptosis through caspase-3 and XIAP/p-Akt pathways." (PMID 36900189, 2023). "Using a variety of available online cancer-related databases including TIMER, cBioPortal, and GEPIA, we identified the abnormal expression of PCSK9 and its potential clinical associations in diverse cancer types including liver, brain and lung." (PMID 37860186, 2023). "Herein, we provide results of a comprehensive pan-cancer analysis of PCSK9 that assessed its prognostic and immunological functions in cancer." (PMID 37860186, 2023). "In patients with HCC, PCSK9 expression was significantly higher in HCC samples than that in para-carcinoma tissues." (PMID 37151886, 2023). "Next, we examined the protein expression of PCSK9 in HCC and para-carcinoma tissues using western blotting and found that PCSK9 was upregulated in HCC tissues." (PMID 37151886, 2023). "This raises a major question about the potential therapeutic benefits of PCSK9 inhibition in these cancers." (PMID 36552895, 2022). "Targeting PCSK9 alone or in combination with statins deserves to be considered as a new treatment modality and assessed in cancer clinical applications." (PMID 36612001, 2022). "As a matter of fact, the expression of PCSK9 is deregulated in many types of cancers such as neuroglioma, breast cancer and colorectal cancer." (PMID 36612001, 2022). "There is growing evidence that PCSK9 expression is deregulated in various types of cancers and malignancies." (PMID 36552895, 2022). "PCSK9 (proprotein convertase subtilisin/kexin type-9), a critical protein that regulates cholesterol metabolism, promotes the incidence and progression of several cancers." (PMID 36110953, 2022). "Statins, competitive inhibitors of HMGCR, and proprotein convertase subtilisin/kexin type 9 serine protease (PCSK9) inhibitors are the mainstays of preventive therapy in cancer patients as in the general population." (PMID 36017084, 2022). "A recent study published in Nature showed that PCSK9 knockout in mouse cancer cells substantially suppressed their growth in mice in a manner that depends on cytotoxic T cells." (PMID 36242053, 2022). "Many published studies have revealed the altered expression of PCSK9 in primary cancers and in cancer cell lines as well as other malignancies." (PMID 36552895, 2022). "The inhibition of PCSK9 led to excessive lipid accumulation and created a void in the defense against oxidative stress, thereby enhancing the vulnerability of cancer cells to ferroptosis." (PMID 36611859, 2022). "The inhibition of PCSK9 was effective in disrupting the oncometabolic process, inducing metabolic exhaustion and enhancing the vulnerability of cancer cells to iron-triggered lipid peroxidation." (PMID 36611859, 2022). "Different studies involving cancer animal models and cancer cell lines showed the high potentiality of PCSK9 as a possible therapeutic target for many diseases." (PMID 36552895, 2022). "The gene was initially designated as NARC1 (neural apoptosis-regulated convertase 1), involved in apoptosis of cerebellar neurons and PCSK9 has since been found to be upregulated in some cancers." (PMID 33886544, 2021). "The Kruskal-Wallis test revealed that patients with any type of cancer had significantly higher levels of s-PCSK9-Abs than HDs, suggesting that s-PCSK9-Ab is a common marker for solid cancers." (PMID 34504788, 2021).
cancer (continued). "It has been suggested that controlling serum PCSK9 level as a low titer contributes to the suppression of cancer development and improving the prognosis of cancer." (PMID 34504788, 2021). "The absence of correlation of antigen and antibody was attributed to the PCSK9 protein assembled in the cancer tissue as detected by immunohistochemistry." (PMID 34504788, 2021). "The roles of PCSK9 in cancer have also been highlighted in terms of regulation of inflammation via a suppressor of cytokine signaling-3-signal transducer and activator of transcription 3 pathway, as well as of cell proliferation and apoptosis." (PMID 34606887, 2021). "We show that proprotein convertase subtilisin/kexin type 9 (PCSK9), a cholesterol-regulating enzyme, plays a pro-survival role in OC and targeting its expression impairs cancer cell growth." (PMID 34359627, 2021). "PCSK9 inhibition also increases cell surface levels of major histocompatibility protein class I in cancer cells and suppresses tumor growth." (PMID 34782856, 2021). "Here, we summarize the latest advances in PCSK9 and focus on its role in lipid metabolism and cancer immunotherapy and the molecular mechanisms for the regulation of PCSK9 expression." (PMID 34782856, 2021). "Our results show for the first time that PCSK9 expression is detected in OC tumor-derived cancer cells or PDCs." (PMID 34359627, 2021). "Concluding, these preclinical data warrant further exploration of PCSK9 inhibitors as cancer therapeutics in clinical trials." (PMID 35097027, 2021). "Nevertheless, these studies suggest that PCSK9 plays a complex role in cancer development via different mechanisms." (PMID 34782856, 2021). "Regarding the relationship between PCSK9 antigen and cancer, several reports have been published that it is better to keep the PCSK9 antigen titer low for improving prognosis." (PMID 34504788, 2021). "Having said this we have to mention that experimental studies suggest that PCSK9 protects cancer cells against apoptosis." (PMID 33364976, 2020). "Our results showed that p38, ERK1/2, and JNK were all activated in the PCSK9-related cancer procedure, and that the modulation of JNK showed a pro-apoptotic effect." (PMID 33489919, 2020). "The interest in studies connecting PCSK9 expression in extra hepatic tissues with the progression of cancer comes from the initial findings that PCSK9 can induce apoptosis in the brain." (PMID 33364976, 2020). "These examples suggest that PCSK9 can protect cells against apoptosis making them more resistant against cancer therapy." (PMID 33364976, 2020). "Using this technique, the research team has shown evidence for lung, liver and spleen specific targeting in mice, and efficient gene editing of PTEN and PCSK9, therapeutic targets for cancer and hypercholesterolaemia, respectively." (PMID 33027946, 2020). "Collectively these data suggest that in cancers that benefit from high LDL-C, PCSK9 improves cancer progression, whereas in cells in which PCSK9 protects against apoptosis it makes cells more resistant against therapy." (PMID 33364976, 2020). "This strategy was used to create organ-specific cancer mouse models by targeting multiple genes in the livers and lungs, and to significantly decrease serum PCSK9 levels in mice." (PMID 33027946, 2020). "HSP70 was screened out and verified from a total of 46 candidate protein molecules interacting with PCSK9 referring to its known function in carcinoma progression." (PMID 33489919, 2020). "In cancer research, PCSK9 could promote tumor growth through lipid metabolism alterations and immune system modulation." (PMID 41311296, 2026). "In addition, PCSK9 is involved in the pathogenesis of various diseases such as atherosclerotic cardiovascular disease, ischemia/reperfusion injury, cancer, and HIV." (PMID 41008547, 2025).